CD4 (CD4 molecule)
Diseases named in the same sentence as CD4 in open-access papers (continued):
Sharing a sentence is not in itself a finding about the gene and the disease.
breast cancer (continued). "Patients with ductal breast cancers infiltrated by high total numbers of CD4+ lymphocytes showed a significantly (p = 0.031) worse overall survival, as compared to patients with lower CD4+ infiltration." (PMID 22471961, 2012). "The interaction between the CXCR4 and the cannabinoid CB2 receptor signaling also modulates chemotaxis of CD4+ T lymphocytes as well as growth and metastasis of breast cancer." (PMID 22998838, 2012). "In a mouse mammary tumor model, IL-4-expressing CD4+ T cells induced TAMs with the M2 phenotype to enhance tumor invasion and metastasis." (PMID 24213108, 2011). "A large study involving 85,268 HIV-infected women in the USA has previously reported a lower SIR for breast cancer, independently of the CD4 count." (PMID 21443771, 2011). "Our previous studies, along with work from other groups, demonstrated that the proportion of CD4+CD25+ Treg subset increased in breast cancer patients, with strong correlations with the histological grade and the tumor size." (PMID 22110525, 2011). "Adjustment for CD4+ cell count, HIV viral load, and use of antiretroviral therapy did not attenuate the association between infection with CXCR4-tropic HIV and breast cancer." (PMID 21179547, 2010). "The maintenance of the CD4+/CD8+ T-cell ratio has been pointed out as an important prognostic factor in the progression of human breast cancer." (PMID 20525350, 2010). "Unilateral irradiation for breast carcinoma has been reported to induce an increase of lymphocytes with elevated CD4/CD8 ratio in broncho-alveolar lavage fluid in both the contralateral and ipsilateral lung soon after radiotherapy." (PMID 17201913, 2007). "The increased CD4/CD8 ratio (4.20) was thought to be a reactive change secondary to chemotherapy for breast cancer." (PMID 16153296, 2005). "Degree of CD28 expression in the CD4+ T-lymphocyte subset in different areas of the sentinel nodes from 21 breast cancer patients (numbers are frequencies)." (PMID 15613231, 2004). "Thus, calcipotriol exhibits a robust antitumor effect in late-stage breast cancer associated with TSLP induction and CD4+ T cell infiltration into the tumors." (PMID 39782693, 2025). "Notably, blocking the recruitment of naïve CD4+ T cells allows the reversal of immunosuppression in breast cancer." (PMID 39888245, 2025). "Our group recently reported, in two late-stage metastatic breast cancer patients, on a novel phenotype of CTCs that, in addition to a strong CK signal, displayed a remarkable set of immune markers characteristic of CD4+ T-cells, including CD45, CD3, CD4, and the stemness marker CD44." (PMID 41301033, 2025). "Furthermore, in mouse mammary tumors, vaccination with tumor antigens (Otud6b, Pdhx or Stk39) induced tumor-specific CD4+ and CD8+ T cells, along with tumor-specific IFN-g T cell and CD8+ T cell responses." (PMID 40651961, 2025). "Similarly, in breast cancer, the accumulation of CD4+ and CD8+ T cells with a senescent phenotype was also reported." (PMID 40870871, 2025). "Notably, CUCA recognized key co-localizations between CD4+_EM_T cells and various T cell subtypes in breast cancer samples from the stnet dataset." (PMID 40662792, 2025). "Hence, identifying the key factors that are involved in CD4+ T cell–mediated tumor immunity in breast cancer will aid in boosting antitumor immunity against this disease." (PMID 39782693, 2025). "Notably, this study also employed RON loss selectively in the myeloid populations of MMTV-RON mammary tumor mice (MMTV-RONΔMyeloid), which phenocopied the increased infiltration of CD8+ and CD4+ T-cells compared to control." (PMID 40282397, 2025). "Thus, calcipotriol and other agents that can induce TSLP will trigger CD4+ Th2 immunity for early and late breast cancer treatment." (PMID 39782693, 2025). "Thus, calcipotriol treatment can be a promising therapeutic treatment for breast cancer by triggering CD4+ T cell–macrophage crosstalk to induce antitumor immunity." (PMID 39782693, 2025).
breast cancer (continued). "Thus, CD4+ Th2 cell activation can suppress breast cancer by inducing antitumor IL-24–expressing TAMs in the TME, which can be leveraged in cancer immunotherapy." (PMID 39782693, 2025). "In humanized models, breast cancer CD4+ T cells have been shown to inhibit tumour growth by arresting cancer cell cycle progression at the G1/S phase, while simultaneously enhancing antitumour immunity through the activation of pro‐inflammatory signalling pathways." (PMID 40673641, 2025). "Breast carcinoma tissue was analyzed by Cobas PIK3CA mutation test for the presence of PIK3CA mutation and immunohistochemistry was applied to assess PD-L1 expression and CD4, CD8, CD68, and CD163 infiltration within tumor." (PMID 41096755, 2025). "In feline mammary carcinomas, increased proportions of CD8+ TILs were linked to extended periods of disease‐free survival and overall survival, while higher proportions of intratumoral CD4+ TILs were associated with positive lymph node status." (PMID 39631747, 2025). "However, the CD8+ T lymphocyte fraction stimulated the BBB-passage of the breast cancer cells more than the CD4+ T-lymphocyte fraction did (p < 0.05)." (PMID 39262976, 2024). "Furthermore, in breast cancer patients, peripheral CD4+ and CD8+ T cells release lower levels of IL-2 and IFN-γ in response to stimulation compared to T cells in the peripheral blood of healthy individuals." (PMID 38702630, 2024). "IL32β was the most abundant isoform transcribed in CD3+ T cells from healthy individuals but also in intratumoral CD4+ Th subsets and circulating TA-specific CD4+ Teff from breast cancer patients, CD4+ and CD8+ MILs from a multiple myeloma patient and TA Survivin-specific CD8+ Teff cells." (PMID 39211051, 2024). "Ing4-deleted mouse mammary tumors contained a significantly reduced number of GzmB+CD4+ T cells." (PMID 38968186, 2024). "Furthermore, assessing the levels of Treg and CD4+T cells in HER-2 (+) patients can be valuable for monitoring the condition of breast cancer patients and predicting the efficacy of anti-HER-2 treatment." (PMID 38263363, 2024). "CD4+ T cells have two subsets—Th 1 and Th 2 cells—and some clinical data observed unbalanced Th 1/Th 2 levels in patients with breast cancer, where Th 2 cells released the cytokines IL-4 and IL-10 and suppressed the host immune system, exhibiting a tumour-promoting effect." (PMID 39624160, 2024). "HLA DR+CD4+%lymphocyte (P = 0.017, OR = 0.956, 95%CI = 0.921~0.992) had a negative causal relationship with breast cancer." (PMID 39418291, 2024). "Moreover, we revealed that CCT2 contributes to breast cancer immune evasion by packaging into breast cancer cell-derived exosomes, where it regulates CD4+ T cell activation through the Ca2+-NFAT1 pathway." (PMID 39079960, 2024). "PKH26-labled exos were cultured with CD4+ T cells for 6 h to determine whether breast cancer cell exos could be taken up by CD4+ T cells." (PMID 39079960, 2024). "In ER+ breast cancer, cell-specific ARPs indicated increased myeloid inflammatory activity, less metabolically active endothelium, attenuated cancer cell interferon responses, and CD4+/CD8+ T cell quiescence and metabolic dysfunction with age." (PMID 39483921, 2024). "A detailed exploration of the activities of CD4+ cytotoxic T lymphocytes could provide a predictive marker for immunotherapy in breast cancer patients." (PMID 39507526, 2024). "Furthermore, the decrease in CD4 + /CD8 + ratio observed in breast cancer patients further revealed the presence of an immunological disorder." (PMID 38834662, 2024). "Similarly, EMT-6 mammary tumor-educated B cells suppress the activation of CD4+ and CD8+ T cells through a TGF-β-dependent mechanism." (PMID 38629061, 2024). "Among these immune phenotypes, the most significant reduction in breast cancer is CD4+ %T cell." (PMID 38327747, 2024).
breast cancer (continued). "Furthermore, the suppression of activin signaling restores CD8+ and CD4+ T cell infiltration and correlates with slowed tumor growth in breast cancer." (PMID 39248018, 2024). "Lastly, mammary tumors displayed modest, albeit nonsignificant, sex-associated differences in the ratios of T-helper (CD4+) and cytotoxic (CD8+) T-lymphocyte subsets." (PMID 39684829, 2024). "The expression of PD-1 on CD4+ TILs is correlated with the invasiveness of breast cancer." (PMID 38533507, 2024). "Hence, serum levels of CD3+T, CD4+T, CD4+/CD8+, DNT, and LMR have significant associations with the development of breast malignant tumors, demonstrating their diagnostic value." (PMID 38263363, 2024). "RANKL is derived from CD4+ FOXP3+ T cells in breast cancer and arthritis." (PMID 38902257, 2024). "We found that SLAMF6 expression was highly correlated not only with the expression of T-cell markers (CD3E, CD8B, CD8A, and CD4) but also with upregulation of TCF7, PDCD1 encoding PD-1, GZMK, and effector-associated genes including IFNG and PRF1 in breast cancer." (PMID 38287061, 2024). "Finally, Arana Echarri and colleagues observed lower counts and activation of CD4+ EMRA T cells following 8 weeks of exercise training in breast cancer survivors (n = 20)." (PMID 39703835, 2024). "the IVW method results showed that CD45RA- CD4+ %CD4+ (p-value:1.37×10−6), CD8dim %T cell (p-value:4.62×10−43), BAFF-R on IgD+ CD38- unsw mem (p-value:6.93×10−5), CD27 on PB/PC (p-value:2.72×10−18) lowered the risk of breast cancer." (PMID 38327747, 2024). "Studies have shown that CD4+ follicular helper T cell infiltration predicts breast cancer survival." (PMID 38420434, 2024). "In addition, pDCs and CD8+ T cells were also found to express HAVCR2 in high expression and CD4+ T cells in lung cancer, while CD4+ T cells in breast cancer and colorectal cancer expressed HAVCR2 significantly lower than CD8+ T cells." (PMID 39120585, 2024). "Treg cells are a subset of T cells with significant immunosuppression, characterized by the expression of Foxp3, CD25 and CD4, which are related to the disease progression and poor prognosis of multiple myeloma, lung cancer, hepatocellular carcinoma and breast cancer." (PMID 38431306, 2024). "Furthermore, compared with that in the control group, the expression of CCT2 in CD4+ T cells decreased following treatment with exos derived from CCT2-knockdown breast cancer cells, whereas CCT2-overexpressing exos had the opposite effect." (PMID 39079960, 2024). "In TN breast cancer we identified proliferating CD4 and CD8 T cells." (PMID 38711512, 2024). "Efforts have been made to restore the crosstalk between DCs and CD4+ T cells by promoting DC maturation, which has shown promising results in conferring potent immunity in breast cancer with CDK4/6 inhibitors (CDK4/6i) and immune checkpoint blockade (ICB) therapy." (PMID 39188717, 2024). "Indeed, the profile of immune cells in the axillary TdLNs is known to provide prognostic value for breast cancer patients, with increased CD4+ T cells and CD1a+ DCs correlating with higher rates of disease-free survival." (PMID 39703517, 2024). "Previous studies have identified a negative correlation between ER expression in breast carcinoma cells and the intratumoral infiltration of lymphocytes, notably CD4+ T cells, CD8+ T cells, B cells, and tumor-associated macrophages (TAMs)." (PMID 39682229, 2024). "Inhibition of naive CD4 T cell recruitment into cancer cells might be a promising strategy in breast cancer." (PMID 36896338, 2023). "We found significant changes in circulating CD4+Th subsets in patients with breast cancer." (PMID 36925914, 2023). "In addition, IL-7Rα expression was reduced on peripheral CD4+ T cells from breast cancer patients compared to healthy donors." (PMID 37741983, 2023). "Therefore, it is of great clinical significance to understand the characteristics of circulating CD4+Th cells in patients with breast cancer." (PMID 36925914, 2023).
breast cancer (continued). "Furthermore, the study observed a significant correlation between KLF2 CNV and infiltration levels of CD4+ T cells and macrophages in breast cancer patients." (PMID 37123417, 2023). "As well as being a risk factor for breast cancer patients, DeNardo DG found that in murine breast cancer models, IL-4 produced by tumor infiltrating CD4 + T cells stimulate M1 to M2 transition of TAMs (Tumor-associated macrophages), thus supporting lung metastasis of breast cancer cells." (PMID 37007080, 2023). "In the context of human breast cancer (BC), Tregs predominantly originate from naive CD4 T cells." (PMID 38235128, 2023). "For example, the lower CD8+ naïve T cell counts and higher CD4+ central memory cell counts among breast cancer survivors, might reflect a previous expansion of effector cells and concomitant shrinking of the naïve T cell pool." (PMID 37324393, 2023). "However, there were a handful of known studies with CD4 T cells related signatures, such as CD4+ conventional T cells-related lncRNA signature in breast cancer and hepatocellular carcinoma prognosis." (PMID 37063862, 2023). "Compound 182 effectively repressed the growth of AT3-OVA mammary tumors and this was accompanied by increased TILs, including increased CD44hiCD62Llo effector/memory and CD44hiCD62Lhi central memory CD4+ and CD8+ T cells." (PMID 37500611, 2023). "For example, regulatory CD4+ T cell (Treg) abundance has been calculated by the xCell algorithm from bulk tumor gene expression data of 5177 breast cancer patients from five independent cohorts, showing the potential of Treg abundance as a biomarker for predicting the response to NAC in TNBC." (PMID 37284197, 2023). "Furthermore, our data also showed that the upregulation of E2F8 was linked to higher enrichments of CD4+ and CD8+ T cells in breast cancers." (PMID 36814821, 2023). "In breast cancer, the copper-depleting compound tetrathiomolybdate (TM) resulted in reduced collagen deposition, decreased levels of myeloid-derived suppressor cells, and increased infiltration of CD4+ T cells." (PMID 37822927, 2023). "Dynamic changes in CD4+Th subsets in patients with breast cancer before and after surgery." (PMID 36925914, 2023). "Furthermore, cytotoxic CD4 T cells from patients with breast cancer, liver cancer and head and neck cancer had significant clonal overlap with non-cytotoxic Th1, Th2 and Th17 CD4 T cells." (PMID 37654482, 2023). "One study used FVB strain erbB2 (HER2) mutant mice with genetic prepositions to mammary tumors and found that when supplied with Lactobacillus reuteri to the gut, the mouse immune system triggered CD4+CD45RBloCD25+ lymphocyte (Treg cells) protective mechanisms to inhibit cancer progression." (PMID 37664075, 2023). "In conclusion, breast cancer and pancreatic cancer are two distinctive cancer types with several common characteristics in aspects of gene, hormone, and inflammatory biomarkers such as IL-6, CD4 or CD8 cells, VEGF and IDO-1." (PMID 37181043, 2023). "Preoperative CD4+Th subsets in the breast cancer and benign tumor groups." (PMID 36925914, 2023). "We observed that the proportion of CD4+Tn cells in breast cancer patients decreased." (PMID 36925914, 2023). "In model mice with a single deficiency in T cell PARP1 or PARP2, there is no change in the number of T cells in peripheral lymphoid tissues, but the double deficiency of PARP1 and PARP2 leads to a reduction in peripheral CD4+ CD8+ T cells in breast cancer model mice." (PMID 38111536, 2023). "In breast cancer, an immune checkpoint blockade increased IL-5 production by CD4+ T cells." (PMID 36980202, 2023). "In breast cancer patients, complete remission in 60% of the combination treatment group in breast cancer patients and there was a significant increase in CD4+ and CD8+ T-cell infiltration and a decrease in MDSCs, M1-type macrophages, and Treg cell infiltration were observed." (PMID 36966334, 2023).
breast cancer (continued). "In agreement with this, but in a different setting characterized by significant inflammation, it has been found that CD39+CD4+ tumor-infiltrating Tconv cells from patients with breast cancer display features of exhaustion while retaining the ability to produce effector cytokines." (PMID 37809093, 2023). "Additionally, a subset of CD4+ T cells aggregate around blood vessels in human breast carcinomas and correlate with poor prognosis." (PMID 38090569, 2023). "A 4-wk treatment with calcipotriol starting when the tumors became palpable (∼5 mm in diameter) led to significant suppression of PyMtOvatg TslprKO breast cancer growth in TslprKO recipient mice that received WT compared with TslprKO CD4+ T cell transfer (P = 0.0067)." (PMID 35657353, 2022). "Based on the GSE114082 datasets, we identified that the TILs with significant differences were M2 macrophages, M0 macrophages, gamma delta T cells, plasma cells, resting memory CD4 T cells, and resting mast cells in breast cancer tissues pre- or posttreated by trastuzumab." (PMID 35317079, 2022). "In breast cancer, the most abundant lymphocyte subtypes that are found are CD4+ and CD8+ T cells." (PMID 35804950, 2022). "Our previously published study, in which we investigated the effect of adding a breast cancer tissue SN) to resting or activated CD4+ T cells of healthy individuals, allowed us to analyze the effect of breast cancer tissue on the signaling pathway activity in CD4+ T cells." (PMID 35158758, 2022). "In breast cancer microarrays, high detection levels of OX40L in a subset of carcinoma associated fibroblast (main component of the stroma) has been associated with the retention of regulatory T cells (i.e., CD4 + CD25+ T cells)." (PMID 36230846, 2022). "Increased numbers of T and B cells in sentinel LNs have been associated with longer DFS across different breast cancer subtypes irrespective of their nodal status, as are increased levels of axillary node CD4+ T cells and DC populations in LN-positive breast cancer patients." (PMID 36139665, 2022). "CXCL13-producing CD4+ Th cells have been reported in patients with breast cancer, in whom they were enriched in tertiary lymphoid structures, and their presence correlated with B cell infiltration and GC maturation at the tumor site and was associated with improved prognosis." (PMID 35439168, 2022). "Importantly, in recurrent mammary tumors, the quantities of CD4(+)/CD25(+)/CD127(−) regulatory T cells (Tregs) present were significantly diminished following postsurgical treatment with olaparib and/or Oligo-Fucoidan." (PMID 36109724, 2022). "Moreover, CODEX analysis of orthotopic mouse mammary tumors demonstrated that inhibiting S100A7/cPLA2 signaling increased the abundance of proliferating as well as activated CD4+ and CD8+ TILs." (PMID 35135586, 2022). "NK, NKT, and CD4+ cells show cytotoxicity against various tumor cells, including breast cancer." (PMID 36304286, 2022). "The recruitment of naïve CD4+ T cells can lead to the immunosuppression of breast cancer." (PMID 36032097, 2022). "CD4 + /Foxp3 + cells are Tregs, and CD4-/Foxp3 + cells might be E0771 breast cancer cells expressing Foxp3." (PMID 36316775, 2022). "Blocking naive CD4+ T cell recruitment into tumors reversed immunosuppression in breast cancer, which may be an attractive strategy for antitumor treatment." (PMID 35494024, 2022). "Clinical results suggest that, in primary breast cancer, the adaptive immune response of CD4+ T cells may be frequently replaced by immunosuppressive Treg cells, potentially causing resistance to checkpoint inhibition." (PMID 35158758, 2022). "We developed a new technology to measure activity of these STPs, which was used to investigate whether CD4+ T cells function abnormally in breast cancer patients." (PMID 35158758, 2022). "Moreover, the estrogen response gene signature, which is involved in enhancing breast cancer progression, was elevated in Cd4+ T cells in the SLN." (PMID 36266717, 2022).